RETN (resistin)
Diseases named in the same sentence as RETN in open-access papers (continued):
Sharing a sentence is not in itself a finding about the gene and the disease.
rheumatoid arthritis (continued). "Most of the data presented by different research groups showed changed levels of leptin, adiponectin, and resistin and occasionally also other adpokines in rheumatoid arthritis and systemic lupus erythematosus." (PMID 22584415, 2012). "All major adipokines (leptin, adiponectin, visfatin, and resistin) bear immune-modulatory properties and evidence points to involvement in the pathophysiology of rheumatoid arthritis (RA)." (PMID 22240096, 2012). "In contrast, synoviocytes from patients with rheumatoid arthritis show that RETN expression is elevated at a site of inflammation." (PMID 17183659, 2006). "Thus, adipose tissue can secrete and release cytokines such as TNFα and IL-6, which are common in inflammatory diseases like rheumatoid arthritis (RA), as well as cytokines known as adipokines (leptin, adiponectin, resistin, and visfatin, among others)." (PMID 40077690, 2025). "Therefore, resistin can be detected locally in the inflamed joint synovium in both rheumatoid arthritis and OA." (PMID 40104308, 2025). "Many clinical reports documented the detection of high levels of resistin in patients with various chronic inflammatory conditions such as rheumatoid arthritis, inflammatory bowel diseases, and chronic kidney diseases and those with oral disease, particularly periodontitis." (PMID 29138754, 2017). "Elevated expression of the CXCL6 gene was observed in OA chondrocytes and FLS-rheumatoid arthritis (FLS-RA) cells stimulated in vitro with IL-1β and resistin (adipokine), respectively." (PMID 36233118, 2022). "Adiponectin, leptin, and resistin are adipocytokines whose levels are elevated in blood and synovial fluid from patients with rheumatoid arthritis (RA)." (PMID 33669910, 2021). "The expression levels of resistin in vitro experiments and OA/rheumatoid arthritis (RA) patients were analyzed." (PMID 30809105, 2019). "Elevated resistin levels have also been shown in patients with rheumatoid arthritis (RA) and inflammatory bowel disease (IBD)." (PMID 24465803, 2014). "Additionally, there is evidence that serum resistin levels are increased in patients with rheumatoid arthritis (RA)." (PMID 27721574, 2016). "Resistin, an adipokine, is expressed in rheumatoid arthritis (RA) or osteoarthritis (OA) patients and in synovial joints after injury, and the plasma resistin level is significantly correlated with erythrocyte sedimentation rate (ESR) and C reactive protein (CRP)." (PMID 25264740, 2014). "Furthermore, resistin may be involved in the pathogenesis of rheumatoid arthritis." (PMID 24072088, 2013). "This may indicate that serum resistin is a non-specific marker of inflammation, which is indirectly confirmed by a decrease in resistin levels observed following anti-TNFα therapy both in IBD and in rheumatoid arthritis." (PMID 31234447, 2019). "Plasma resistin levels were 12.1, 10.8, and 10.0 ng/ml in participants with rheumatoid arthritis, with osteoarthritis, and without arthritis, respectively (P = 0.49, n = 240)." (PMID 29225423, 2017). "Increased serum resistin in patients with rheumatoid arthritis correlated with both C-reactive protein (CRP) and DAS28, suggesting a role of this adipokine in the pathogenesis of rheumatoid arthritis." (PMID 22910888, 2012). "On the other hand, age, gender, alcohol consumption, coronary heart disease, rheumatoid arthritis, the use of oral corticosteroids or NSAIDs, body mass index, and the serum proinflammatory markers resistin, hs-CRP, TNF-α, and IL-6 were not significantly related to logLSburden." (PMID 23902899, 2013).
coronary artery disease (48 papers, 2005 to 2026). "The resistin-rising allele (C-allele) of TYW3/CRYZ SNP rs3931020 was associated with increased coronary heart disease risk." (PMID 34805208, 2021). "The data is consistent with prior studies indicating an inverse correlation of myeloid cell counts with T2D, coronary heart disease and inflammatory diseases, all of which are positively associated with RETN expression." (PMID 31645609, 2019). "It should be noted that increased resistin level is also associated with coronary heart diseases in general population." (PMID 31842758, 2019). "We previously reported in this population a direct association between resistin and the risk of ischemic heart disease, and between this cytokine and saturated fat intake and serum triglyceride concentration." (PMID 28771611, 2017). "A European study of more than 20,000 healthy individuals found a higher risk for the development of myocardial infarction, stroke, coronary artery disease or impaired renal function in those in the highest quartile of resistin." (PMID 24465803, 2014). "There is increasing evidence from human clinical and experimental studies that resistin has a pathogenic role in the development and progression of atherosclerosis, coronary artery disease (CAD), and even heart failure." (PMID 23171632, 2012). "In relation to other CVDs, the opposite results were described in the previous literature, wherein resistin was highlighted as an independent risk factor for coronary arterial disease, myocardial infarction, and heart failure, whereas it is linked to atrial fibrillation." (PMID 37238961, 2023). "In a model comprising age, sex, smoking habits, BMI, HbA1c, and insulin, antihypertensive and antidyslipidemic therapies, serum resistin was associated with coronary artery disease in both cross-sectional studies: OR (95%CI) per SD increment = 1.35 (1.10–1.64) and 1.99 (1.55–2.55)." (PMID 23755138, 2014). "We evaluated the association between serum resistin and aortic stiffness in patients with coronary artery disease (CAD)." (PMID 28806778, 2017). "Acute inflammatory conditions disproportionately elevate resistin compared to chronic stable cardiovascular diseases, constraining its utility in stable coronary artery disease or early-stage heart failure with preserved ejection fraction." (PMID 41347124, 2025). "In patients with coronary artery disease, serum resistin has emerged as an independent marker of aortic stiffness." (PMID 37763771, 2023). "Plasma concentration parameters of adiponectin and resistin measured in echocardiographic examination of coronary artery disease (CAD) patients were found to be related to cardiac remodeling and dysfunction." (PMID 35890325, 2022). "Future endeavors in this direction, overcoming the study limitations, will help in better understanding of the links between the triad of resistin, inflammation and coronary artery disease." (PMID 31258568, 2019). "Subsequent studies have found an association of resistin and CAP1 with conditions like coronary artery disease and rheumatoid arthritis." (PMID 30018317, 2018). "Clinical characteristics and serum resistin levels of the 104 patients with coronary artery disease." (PMID 28806778, 2017). "Moreover, additional reports suggest that resistin has a pathogenic role in the development and progression of atherosclerosis and coronary artery disease (CAD)." (PMID 28806778, 2017). "Correlation between serum resistin levels and clinical variables among the 104 patients with coronary artery disease." (PMID 28806778, 2017). "Plasma resistin levels were significantly higher in patients with coronary artery disease (CAD) and in individuals with acute inflammatory disease than controls, and correlated with markers of inflammation predicting coronary atherosclerosis in humans." (PMID 23484124, 2013).
coronary artery disease (continued). "Further investigations, especially those involving a larger number of samples, are necessary to clarify the role of resistin in the development of hemorrhagic stroke and coronary artery disease." (PMID 19922611, 2009). "The relationship between resistin and coronary artery disease is highly controversial, and the information regarding resistin and ischemic stroke is limited." (PMID 19922611, 2009). "Similarly, resistin shows minimal correlation with angiographic coronary disease severity scores or echocardiographic markers of diastolic dysfunction in stable cohorts." (PMID 41347124, 2025). "In acute coronary syndrome and ischemic heart disease, high resistin levels could be a biomarker of injury." (PMID 38227584, 2024). "Serum levels of specific adipokines, including leptin, adiponectin, resistin, and retinol-binding protein 4 (RBP4), have been associated with the presence of coronary artery disease (CAD), suggesting a potential role of these adipokines in the pathogenesis of CAD." (PMID 36964443, 2023). "Our preceding research has further indicated that serum resistin levels could serve as a potential biomarker for aortic stiffness in patients with coronary artery disease (CAD)." (PMID 37763771, 2023). "In patients with symptomatic coronary artery disease, a correlation was discovered with resistin." (PMID 36299943, 2022). "In that same study, it has shown that leptin and resistin are linked with coronary artery disease regardless of CRP." (PMID 36299943, 2022). "Resistin is a cytokine related with inflammation and ischemic heart disease." (PMID 28771611, 2017). "It has been shown that EAT produces inflammatory mediators such as interleukin (IL)-6, IL-1b, tumor necrosis factor (TNF)-a, and monocyte chemotactic protein (MCP-1) in patients with significant coronary artery disease and expresses mRNAs of adiponectin, resistin, leptin, IL-6, TNF-a, and CD-45." (PMID 23762053, 2013). "Elevated resistin opposed to adiponectin plasma levels was proposed to be a strong predictive factor for the occurrence of major adverse cardiac events in patients with stable multivessel coronary artery disease over 1-year follow-up." (PMID 21251282, 2011). "This study examines the association between human serum resistin, T2DM and coronary heart disease." (PMID 15998471, 2005). "Resistin acts on endothelial dysfunction and CVD, where, for example, in patients with severe ischemic heart disease or hypertension, its levels are higher than in healthy controls, and the more influential the ischemic heart disease is that is diagnosed, the higher the serum resistin levels are." (PMID 38139115, 2023). "Over time, elevated levels of resistin have been associated with increased risk of coronary heart disease, especially with myocardial infarction (but not with stroke) and with the degree of heart failure, both responsible for increasing the rate of cardiac events, including the risk of death." (PMID 31881807, 2019). "Indeed, circulating resistin is significantly increased in patients with previous myocardial infarction, while it is positively correlated with markers of inflammation in patients with coronary artery disease (CAD) and the risk of heart failure in the Framingham Offspring study." (PMID 23484124, 2013). "However, serum resistin levels do not add prognostic information among high-risk persons with established coronary heart disease." (PMID 21251282, 2011). "However, the relationship between resistin and coronary artery disease is highly controversial." (PMID 19922611, 2009). "In coronary artery disease (CAD) patients, resistin correlates with the number of stenotic vessels and predicts major adverse cardiovascular events, including myocardial infarction and cardiovascular death." (PMID 41347124, 2025). "In an average follow-up of 83.4 months, resistin levels were an independent predictor of a new acute ACS in patients with coronary artery disease." (PMID 30405857, 2018).
coronary artery disease (continued). "As compared with controls, all patients with coronary heart disease (including SA and ACS) have higher levels of hs-CRP and resistin, but lower levels of adiponectin." (PMID 26986475, 2016). "Likewise, the lack of association between either hemorrhagic stroke or coronary heart disease and serum resistin may be reflection of the small samples." (PMID 19922611, 2009). "The relationship between resistin and atherothrombotic-related diseases such as cardiovascular and coronary heart disease has been clearly established in individuals, regardless of ethnicity and race." (PMID 34445740, 2021). "We aimed to investigate the relationships of resistin, retinol-binding protein 4 (RBP4) and adiponectin produced by epicardial adipose tissue with coronary artery disease (CAD) and cardiac structure and function." (PMID 36964443, 2023). "Moreover, in a cohort of patients, resistin has been shown to be an independent predictor of acute coronary syndromes (ACS) (in patients without a history of myocardial infarction or stroke) and for cardiac or cerebrovascular events (in patients with coronary artery disease)." (PMID 30405857, 2018).
Hyperglycemia (43 papers, 2007 to 2025). An increased concentration of glucose in the blood. "In vivo, as expected, STZ treatment of rats caused hyperglycaemia and insulin, adiponectin and resistin deficiencies." (PMID 18353182, 2008). "Hyperresistinemia created by acute resistin infusion or stable resistin gene transfer causes IR in rodents, whereas its absence protects from diet-induced hyperglycemia as well as IR in ob/ob mice by increasing AMPK activity and decreasing the levels of gluconeogenic enzymes in the liver." (PMID 33671547, 2021). "Thus, our findings further characterize resistin as an inflammatory cell-derived factor that responds to hyperglycemia and metabolic stresses associated with diabetic pregnancy." (PMID 32762639, 2020). "Key adipokines such as leptin, resistin, and ghrelin disrupt insulin signaling, inhibit glucose receptor activity, and contribute to hyperglycemia." (PMID 39596980, 2024). "In the high‐sucrose diet group, anxiety symptoms correlated with metabolic syndrome, which showed hyperglycemia and the reduction of leptin and resistin." (PMID 37927197, 2024). "For some authors, resistin is a marker of maternal hyperglycemia, increases in late pregnancy and during the immediate post-birth period, and is associated with the HOMA-IR index." (PMID 27651836, 2016). "Additionally, resistin responds to hyperglycemia and metabolic stress, which has a potential role in regulation of placental mitochondrial abundance and function." (PMID 38610889, 2024). "As a result of acute hyperglycemia, resistin is up-regulated in various adipose depots." (PMID 38227584, 2024). "Antiresistin RNA oligo treatment significantly reduced serum glucose level associated with downregulation of PEPECK expression, suggesting that inhibition of resistin may be a potential therapy for hyperglycemia through downregulation of hepatic PEPCK." (PMID 25922835, 2015). "Resistin is produced and secreted mainly by mononuclear cells in peripheral blood, and hyperglycemia-induced monocyte/macrophage activation may lead to increased secretion of resistin." (PMID 24072088, 2013). "Postprandial hyperglycemia is associated with lower circulating leptin whereas resistin and adiponectin are not altered in slim, insulin-sensitive probands." (PMID 17311679, 2007). "Furthermore, resistin restored the microbicidal activity of colostrum cells from diabetic mothers but not from mothers with comorbidities, suggesting a possible effect of this hormone on the colostrum of mothers with hyperglycemia." (PMID 36289594, 2022). "A possible explanation for higher apoptotic cell indices may be the association of hyperglycemia and low-grade inflammation, since exogenous resistin did not change the percentage of cells expressing CD95+ or the apoptosis." (PMID 36289594, 2022). "Interestingly, NFATc expression pattern highly resembled that of resistin expression, suggesting that hyperglycemia-induced resistin upregulation may be a result of aberrant activation of NFATc, which may transcriptionally regulate resistin expression." (PMID 30353146, 2018). "In the present research, HSHF not only induced the formation of hyperglycemia but also increased the levels of serums TC, TG, LDL-C, resistin, and LEP, and decreased the level of ADPN." (PMID 37569125, 2023). "Hyperglycemia can contribute to tumor-related inflammation by triggering the release of pro-inflammatory cytokines such as interleukin-6 (IL-6), interferon γ (IFN-γ), tumor necrosis factor-alpha (TNF-α), and resistin." (PMID 39064000, 2024). "The lack of difference in relation to hyperglycemia for milk leptin, adiponectin, leptin–adiponectin ratio, resistin, and IGF-I levels might be the outcome of effective treatment of GDM during pregnancy." (PMID 38612666, 2024).
Hyperglycemia (continued). "In contrast to leptin, adiponectin and resistin were not altered 2 h after glucose uptake and this is in agreement with recent studies indicating that systemic adiponectin and resistin are not influenced upon acute hyperglycemia and/or hyperinsulinemia." (PMID 17311679, 2007). "A difference was found for milk ghrelin, but not for molecules such as adiponectin, leptin, resistin, or IGF-I levels, in relation to maternal hyperglycemia." (PMID 38612666, 2024). "The lack of difference in the pattern of leptin, adiponectin, LAR, resistin, and IGF-I levels between GDM and non-GDM mothers observed in our study might be the outcome of the implementation of quick and effective treatment of hyperglycemia during pregnancy." (PMID 38612666, 2024).